MMP1 (matrix metallopeptidase 1)
Diseases named in the same sentence as MMP1 in open-access papers (continued):
Sharing a sentence is not in itself a finding about the gene and the disease.
cancer (continued). "MMP-1 is thought to be involved in cancer progression and invasion, whereas the mechanism by which MMP-3 contributed was not clarified." (PMID 28446168, 2017). "Unexpectedly, we identified MMP1 mRNA in EVs derived from a highly metastatic cancer cell line, ES-2 and patient ascites, and found that it was associated with the malignant phenotypes." (PMID 28262727, 2017). "Given the important role of MMP1 both in mechanism of cancer carcinogenesis and clinical application, we carried out this research to assess the clinical and prognostic importance of MMP1 in BC." (PMID 29207651, 2017). "Some of them have been reported to be cancer-associated genes such as CDC25A, CDKN1A, MMP1, MMP13 and SOX4." (PMID 27863388, 2016). "MMP1 is highly expressed in many types of cancer, specifically BC in Western populations, and positively correlates with accelerated cell migration, advanced clinical stage and metastasis in BC, making MMP1 a significant predictor of poor prognosis in BC29." (PMID 27857161, 2016). "The results of zymography showed that C6-shHdj2 cells possess highly active MMP-1 and -2, whose activation was already demonstrated in a variety of human cancers." (PMID 26959111, 2016). "We then examined the influence of EGF on MMP9 transcription as well as on the transcription of additional MMPs (MMP-1, MMP-2, MMP-3, MMP-7, MMP-10, MMP-13, MMP14, MMP15) and of CD44, a cell adhesion glycoprotein implicated in EMT and cancer metastasis." (PMID 26084289, 2015). "The MB-downregulated genes include cancer-associated cytokines/chemokines (e.g. CXCL1, CXCL2, CXCL3, CXCL14, IL1A, IL1B, IL6, IL8) and matrix metalloproteinases (MMP1,MMP9)." (PMID 25642713, 2015). "Among the 52 cancer metastasis genes that we examined, four genes that code for MMP1, 3, 10, and 13 were significantly induced in RKIP knockdown 168FARN cells and were greatly repressed in 4T1 RKIP-expressing cells (data not shown)." (PMID 26308852, 2015). "HGF-induced FAK phosphorylation simultaneously upregulates many matrix metalloproteinases like MMP-1, -9, and -14, through activation of the transcription factor Ets, in cancers of the gallbladder, prostate, and liver thereby facilitating cancer invasion." (PMID 26404380, 2015). "Expression of MMP-1 has been observed in various cancers such as breast, colorectal, gastric and esophageal cancer, and contributes to cancer progression." (PMID 24531055, 2014). "These genes are related to DNA damage repair (Atm), act as transcription factors (Fos and Myc), or perform important roles in cancer-cell invasion (Mmp1)." (PMID 24928374, 2014). "MMP-1 mRNA was seen in HCC cells infiltrated into the small portal tract left in tumor nodule as well as in the fibrous bands surrounding the cancer cell nodule." (PMID 24978432, 2014). "The effect of HDF-conditioned culture media on the expression of MMP-1, -2 and -9 was examined, which are all marker proteins of cancer metastasis." (PMID 25013462, 2014). "A subsequent study revealed that MMP-1 expression was significantly different in primary and metastatic CRC, with strong MMP-1 expression seen in primary cancers with lymph node involvement, but decreasing MMP-1 expression observed in metachronous metastases." (PMID 24518611, 2014). "MMP-1-positive clones (well-differentiated cancer cells) are compressed by new clones (moderately differentiated cancer cells) and subsequently disappear." (PMID 24978432, 2014). "Polymorphisms in the MMP1, MMP2, MMP3, and MMP9 genes have been examined in studies evaluating cancer metastasis and functional polymorphisms have been identified for these genes." (PMID 23696797, 2013). "In human cancer cells, MMP-1, MMP-2, MMP-3, MMP-9, and MMP-13 have been found to be correlated with malignant grade and metastasis." (PMID 24047437, 2013).
cancer (continued). "Consistent with this prediction, increased expression of the cancer invasion-related genes matrix metalloproteinase (MMP)-1, MMP-2, epidermal growth factor receptor (EGFR) and cyclooxygenase 2 (COX-2) were detected in the CD44+ stem-like cells." (PMID 23833643, 2013). "Taken together, these results indicate that AEG-1 is able to increase the invasive ability of cancer cells by increasing MMP1 expression." (PMID 24063540, 2013). "Downstream from MAPK signaling, JNK activation helps regulate cancer cell invasion and expression of MMP-1, MMP-2, and MMP-9." (PMID 23878609, 2013). "Collectively, these results suggest that MMP-1 is an important target for treating cancer metastasis." (PMID 23892595, 2013). "Subsequently, the cancer invasion factors uPA, MMP-1 and MMP-13, and cell invasiveness, were decreased." (PMID 23401122, 2013). "Polymorphisms in MMP1 −1607, MMP3 −1171 and MMP9 −1562 have been associated with general cancer metastasis in a large meta-analysis." (PMID 23696797, 2013). "In our study, we have shown that AEG-1-knockdown SAS and FaDu cells reduce both the invasive ability of cancer cells and the expressions of MMP1." (PMID 24063540, 2013). "Our work and the work of others have clearly demonstrated effects of Fra-1 and MMP-1 in multiple cancer systems." (PMID 25339983, 2013). "It is therefore conceivable, that the results presented in this study also provide mechanistic insight into the role of MMP-13 and MMP-1 in the progression of these malignant tumors." (PMID 22880047, 2012). "The results of meta-regression for MMP1 (−1607) 1G/2G indicated that cancer site and ethnicity of study population independently contributed to the heterogeneity observed under dominant and recessive models (data not shown)." (PMID 22348060, 2012). "Transcriptional regulators of MMP-1 in cancer cells include STAT3 and members of the AP-1 family of transcription factors." (PMID 23217186, 2012). "In our comprehensive meta-analysis, MMP1 (−1607)1G/2G, MMP7 (−181) A/G and MMP9 (−1562) C/T were shown to increase the risk of cancer metastasis, whereas MMP3 (−1171) 5A/6A was protective in metastasis." (PMID 22348060, 2012). "Matrix metalloproteinase-1 (MMP-1) expression has been reported to inversely correlate with survival in advanced cancers." (PMID 21835023, 2011). "The two other genes in our OSCC recurrence signature (COL4A1 and MMP1) are better characterized in cancer." (PMID 21989116, 2011). "It appears that once secreted, MMP-1 promotes cancer cell invasion through degradation of extracellular matrices and/or submucosal layers of lymphatics." (PMID 21966428, 2011). "Specifically, a previous study showed that a SNP on MMP-1 promoter created a novel ETS binding site that augmented the MMP-1 transcription in cancer cells." (PMID 21445343, 2011). "In a previous study MMP-1 expression and PR expression had a statistically significant inverse correlation with CAFs and cancer cells." (PMID 21835023, 2011). "Its roles have undergone extensive research in areas of prevention and therapy of cancer; it has been shown that MMP-1 mRNA and MMP-2 and -9 activities are inhibited by glutathione in human fibroblasts and liver allografts, respectively." (PMID 21118526, 2010). "MMP-1 is a fibroblast-type or interstitial collagenase and majorly secreted from fibroblasts, keratinocytes, macrophages, but also cancer cells." (PMID 20946664, 2010). "Matrix metalloproteinase (MMP)-1 promotes ultraviolet (UV)-triggered long-term detrimental effects such as cancer formation and premature skin aging." (PMID 19287485, 2009). "This regulation is lost in the epithelial cancer cell line Caco-2 which responds with MMP-1 production after generation of ceramide by exogenous SMase alone." (PMID 19787068, 2009). "MMP-1 promotes ultraviolet (UV)-triggered long-term detrimental effects like cancer formation and premature skin aging." (PMID 19287485, 2009).
cancer (continued). "The most extensively studied MMP SNP in relation to cancer is the −1607 bp insertion/deletion in the MMP-1 promoter." (PMID 17311017, 2007). "Although the MMP family has long been suggested as promising targets in cancer, remarkably only three – MMP1, -2, -7 – we consider to have been experimentally validated sufficiently to be designated as cancer targets." (PMID 16538215, 2006). "Matrix metalloproteinase-1 (MMP-1) is involved in the degradation of interstitial collagen and thus thought to play a role in invasion of carcinoma." (PMID 11161388, 2001). "MMP-1 mRNA was demonstrated to be expressed exclusively in almost all carcinoma tissue specimens (T) (94.1%) by reverse transcription-polymerase chain reaction, but not found in normal mucosal tissue specimens (N)." (PMID 11161388, 2001). "In addition, this gene was found to co-express with MMP1 and CXCL5 in a subset of cancer-associated fibroblasts associated with poor clinical outcome." (PMID 41489684, 2026). "We were the first to find that activating MAPK pathway, which was suggest by KEGG enrichment analysis, in platinum-resistant EOC cells leads to the upregulation of MMP1.The upregulation of MMP1 is suggest to promote cancer cell proliferation, invasion, and metastasis in cancers." (PMID 40535817, 2025). "MMP-1 expression has been particularly implicated in classifying atypical ductal hyperplasia into being versus pre-malignant lesions, reinforcing the ECM role in cancer progression and risk assessment." (PMID 41281748, 2025). "Furthermore, SERPINE1 interacts with various proteins such as TGFB1, FN1, MMP1, influencing cancer cell adhesion, and motility." (PMID 39817507, 2025). "MMP1 has been extensively studied for its role in drug resistance across various cancers." (PMID 40287412, 2025). "According to certain studies, using inhibitors that bind to the catalytic site of MMP-1 could be a potential alternative therapy to halt the progression of cancer during its early stages." (PMID 40176865, 2025). "The VM formation ability of cancer cells were also regulated by MMP1." (PMID 40885703, 2025). "Importantly, other studies have confirmed that infection with P. gingivalis increased the production and activity of MMP-1, -2, -7, -9, and -10 in cancer cells by modulating the IL-8/MMPs axis." (PMID 41228271, 2025). "Additionally, MMP1 facilitates cancer progression by directly remodeling the ECM, targeting numerous ECM components for proteolysis." (PMID 40362553, 2025). "MMP1 antibody-conjugated material can be used to diagnose cancers with high concentrations of MMP1." (PMID 38320998, 2024). "This up-regulation might be related to the general tendencies of MMPs in cancer, where MMP1 is significantly and almost universally up-regulated, and MMP3 and MMP12 show significant up-regulation in at least 10 types of cancer." (PMID 39596132, 2024). "Importantly, the role of MMP1 in inhibiting the proportion of TILs and weakening the killing ability of T cells against cancer cells provides new insights for future research and clinical treatment of HNSCC." (PMID 39629135, 2024). "Notably, PRDX3 expression was positively correlated with MMP-1 expression in both epithelial (Spearman’s rho = 0.2868, P < 0.001) and stromal parts (Spearman’s rho 0.2205, P < 0.01) of cancer tissues." (PMID 38321552, 2024). "In addition, pan-dCAFs expressed high levels of COL11A1, COL1A1, MMP11 and MMP1, which are closely related to cancer invasion." (PMID 38827236, 2024). "Compared to the stringent control of PAR1 activation in normal tissues, PAR1 is constitutively overexpressed by cancer cells through activation of many downstream signaling cascades including the MMP1, signal transducer and activator of transcription 3 (STAT3), AKT, and VEGF pathways." (PMID 37667257, 2023).
cancer (continued). "As HLCS knockdown cells showed marked reduction of invasion accompanied by reduced MMP1 expression, we checked whether these defective phenotypes were attributed to impaired epithelial-mesenchymal transition program and stemness of cancer cells." (PMID 38283944, 2023). "Although inhibition of matrix metallopeptidases, including MMP1, is, in principle, attractive for cancer therapy, the complexities of their functions as well as the nonselectivity of current inhibitors are likely underlying causes for their failure in clinical trials." (PMID 37870957, 2023). "Similar types of MMPs are increased in both cancers, namely, MMP-1, MMP-2, MMP-9, and MMP-11." (PMID 36982551, 2023). "Of note, MMP-1 was inhibited in both cancer cell lines grown on the C60 nanofilm." (PMID 38067256, 2023). "Notably, the identification of some Mmps (Mmp1, Mmp2, Mmp7 and Mmp9) has been reported as Myb-regulated genes in cancer cells." (PMID 37701782, 2023). "Moreover, it was reported that resistance towards cetuximab induced by cancer-associated fibroblasts (CAF-)-induced cetuximab resistance in head and neck squamous cell carcinoma was mediated by MMP-1 expression." (PMID 35586209, 2022). "In addition, we conducted correlation analysis between MMP1 and immunomodulators on all cancers of TCGA." (PMID 35948625, 2022). "Furthermore, we demonstrated that MMP1 is a driving factor to induce tam resistance using transplanted cancer cells." (PMID 35267540, 2022). "It was observed that MMP-1 gene silencing inhibited cancer cell growth and promoted apoptosis." (PMID 35586209, 2022). "In addition, bioinformatics analysis results also indicated MMP1 has involved in significant cancer-related pathways such as PI3K-Akt signaling pathway, focal adhesion, MAPK signaling pathway, and cell cycle." (PMID 36105241, 2022). "Belonging to the matrix metalloproteinase protein family, MMP-1 is an interstitial collagenase that degrades collagen and may be involved in cell migration, cell proliferation, the pro-inflammatory effect, and cancer progression." (PMID 36421137, 2022). "However, systematic pan-cancer analysis based on big data on the correlation between MMP1 expression and clinical manifestations of various tumors has not been explored." (PMID 36727076, 2022). "However, additional molecular studies are required to further elucidate other possible pathways activated by MMP-1 in regulating chemoresistance and cancer metastasis." (PMID 35586209, 2022). "Therefore, the induction of MMP1 in cancer cells treated with antiplatelet agents was investigated at the mRNA and protein levels by qRT-PCR and Western blotting." (PMID 36076991, 2022). "Finally, the MMP-1 concentration in the A549 human lung (carcinoma) culture medium was measured, and this determination accuracy was confirmed using an ELISA assay." (PMID 36421137, 2022). "Finally, MMP-1, produced by A549 human lung (carcinoma), was collected in the culture media and then determined with MIP film-coated electrodes." (PMID 36421137, 2022). "Secreted MMP-1 has been used as a prognostic marker for several types of cancers." (PMID 35127864, 2021). "Thus, the inhibition of ECM remodelling by targeting MMP1 activation is considered a critical step in cancer therapy." (PMID 34445346, 2021). "PLAU1 and MMP1 play similar roles in malignant tumors and exhibit a high degree of connectivity." (PMID 33816223, 2021). "Nevertheless, of the total number of patients analyzed with cancer, we identified that MMP-1 staining intensity and MMP-3 staining percentage and intensity were significantly increased in the cancerous tissues by 62.3% and 67.5%, respectively, compared to the normal mammary tissues." (PMID 34445715, 2021). "In the 18 cancer types from TCGA, we calculated tissues with mutations of ADAM12, MMP1, SERPINE1, PLOD3, and P4HA3, and they had limited mutations, and their mutation sites had few significant effects on gene expression or function gain across the 18 cancer types." (PMID 34121340, 2021).
cancer (continued). "Thus, inhibition of MMP-1 through suppressing any of the MAPK pathway regulators—JNK/ERK—induces cell death in cancer cells." (PMID 33921173, 2021). "Cancer can produce a wide spectrum of proteases, including MMP-1, MMP-3, MMP-7, MMP-8, and MMP-14." (PMID 34769032, 2021). "We thus conclude that the ADAM12, MMP1, SERPINE1, PLOD3, and P4HA3 signature showed a close association with a pan‐cancer effect on prognosis and is related to ECM proteins in the TME which corresponding with immunologically “cold” cancer types." (PMID 34121340, 2021). "By incubating the hydrogel in MMP‐1 the elastic modulus was reduced from 4 to 0.5 kPa, this modification of the mechanical properties promoted cancer cells proliferation, and at the same time led to a reduced expression of E‐cadherin and lower detoxification capacity." (PMID 33643799, 2021). "Interestingly, while the MMPs members from MMP1 to MMP14 were generally upregulated in several cancer types, the others (MMP15 to MMP28) were downregulated." (PMID 34830271, 2021). "Both cancer cells and stromal cells were positive for MMP-1 in ADC." (PMID 33905434, 2021). "It was also reported that MMP-1 is the most important factor in cancer development." (PMID 34078895, 2021). "Growing evidence has shown that MMP1 plays critical roles in tumourigenesis and cancer metastasis." (PMID 32300605, 2020). "Several synthetic inhibitors of MMP-1 were developed and trialed in various cancer types." (PMID 33002044, 2020). "The quantitative Reverse transcription polymerase chain reaction (qRT-PCR) assay revealed that the Messenger RNA (mRNA) of SAA-1 and SAA-4 was much higher in cancer tissues than in adjacent tissues, and MMPs was up-regulation including MMP-1, MMP-9 and MMP- 12 in OVCAR-3 cell stimulated by SAA." (PMID 32517794, 2020). "According to our analysis, salivary MMP-1 levels in OSCC patients with poorly differentiated cancer (G3) were higher than those in patients with undifferentiated or well-differentiated (G0-1) cancers." (PMID 32823758, 2020). "In addition, studies have shown that 14-3-3σ also induces overexpression of matrix metalloproteinase 1 (MMP-1), a proteolytic enzyme that degrades native fibrillar collagens, and is often associated with poor prognosis in malignant tumor." (PMID 33287252, 2020). "In addition, cancer-derived exosomes carry matrix metalloproteinase 1 (MMP1) mRNA to induce apoptosis in recipient mesothelial cells." (PMID 31188849, 2019). "Interestingly, several genes associated with cancer cells invasion were downregulated upon HPSE knockdown, including MMP1, MMP7, MMP10, MMP13, and CEACAM6." (PMID 31001480, 2019). "Notably, our study showed that MMP1 was targeted by adenine and oxymatrine, and previous evidence has indicated that oxymatrine inhibits the proliferation and facilitates apoptosis of cancer cells through downregulating MMP2 and MMP9 expression." (PMID 31275410, 2019). "Finally, module 4 included the genes PLCB4, MMP1, CTNNB1, EGF, F2R, and LPAR4, associated with pathways in cancer, Rap1 signalling pathway, and phospholipase D signalling pathways." (PMID 31178673, 2019). "In addition, high expression levels of TGFβ and MMPs at the aggregation point of the NIH3T3 cells and collagen matrix showed that TME-resident fibroblasts affected cancer cells via the storage of MMP1 and MMP9 in the ECM." (PMID 29403007, 2018). "Moreover, MMP1 mRNA-carrying EVs exist in the ascites of cancer patients and these EVs also induce apoptosis in mesothelial cells." (PMID 28262727, 2017). "Interestingly, the caspase activities in HPMCs treated with the patient-derived EVs with high amounts of MMP1 mRNA (cancer 1 and cancer 2) were significantly increased and the morphology of the HPMCs was altered in a similar manner to the ES-2 EV treatment." (PMID 28262727, 2017). "However, in the presence of heparin, tryptase increased cancer cell migration and expression of activated MMP-1." (PMID 28315938, 2017).